NGF (nerve growth factor)
Diseases named in the same sentence as NGF in open-access papers (continued):
Sharing a sentence is not in itself a finding about the gene and the disease.
osteoarthritis (continued). "Of interest is the fact that, in the conditions adopted, the inhibition of the receptor is not complete; the latter effect is considered as having negative consequences as shown when using NGF monoclonal antibodies in osteoarthritis." (PMID 38203377, 2023). "Longitudinal studies of horses from the detection of early osteoarthritis without structural changes until more chronic, structural lesions develop would be helpful for determining changes in serum NGF concentration with disease progression." (PMID 37083137, 2023). "All horses in the advanced osteoarthritis group had radiographic evidence of osteophytes, and thus serum NGF concentration is not solely dependent on the absence or presence of advanced osteoarthritic disease." (PMID 37083137, 2023). "In studies employing human peripheral blood monocytes, the results are unclear as expression of NGF, TrkA, and p75NTR is reported in monocytes but not in macrophages and in a macrophage subpopulation isolated from patients with osteoarthritis." (PMID 31996225, 2020). "In the last few years, nerve growth factor (NGF), a key molecule involved in the regulation of neuronal regeneration during injury and pain perception, has been suggested as a promising target for osteoarthritis (OA) treatment." (PMID 32121192, 2020). "Within the context of the anti-NGF clinical trials, these types of rapid progressive osteoarthritis usually (but not always) manifest in a joint in which osteoarthritis was already present." (PMID 32471412, 2020). "Nerve growth factor (NGF) has a pivotal role in peripheral hyperalgesia and inflammation; anti-NGF antibodies attenuate pain responses in inflammatory pain models, and in people with osteoarthritis (OA) or low back pain." (PMID 27208420, 2016). "Tropomyosin receptor kinase A (TrkA) mediates nociceptor sensitisation by nerve growth factor (NGF), but it is unknown whether selective TrkA inhibition will be an effective strategy for treating osteoarthritis (OA) pain." (PMID 26286016, 2016). "Though data from human trials conducted on CRPS patients are not available, anti-NGF has the ability to reduce other forms of refractory chronic pain in humans including back pain and pain due to osteoarthritis." (PMID 22824437, 2012). "This assumption, however, is not mirrored in osteoarthritis, in which anti-NGF therapy has been shown to provide analgesia that was not accompanied by anti-inflammatory effects." (PMID 22761785, 2012). "Biological therapies like monoclonal antibodies (mAbs) against nerve growth factor (NGF) (e.g., tanezumab) and calcitonin gene-related peptide (CGRP) (e.g., erenumab) have shown promise in the treatment of chronic pain conditions such as osteoarthritis and migraines." (PMID 41012116, 2025). "In addition, in the mouse model of osteoarthritis-induced pain, it was found that MSC-EVs could normalize the hyperexcitability of nerve growth factor (NGF)-induced sensory neurons and significantly reduce pain-like behavior in mice." (PMID 39020426, 2024). "However, an important mediator of pain in human and animal osteoarthritis, Nerve Growth Factor (NGF), although expressed in all our osteocyte cultures, was not regulated by load (Padj = 0.067)." (PMID 39157681, 2024). "Five horses had advanced osteoarthritis and did not have detectable serum NGF concentrations." (PMID 37083137, 2023). "A recent phase 3 study demonstrated that treatment with tanezumab, a nerve growth factor inhibitor, or nonsteroidal anti-inflammatory drugs (NSAIDs) improves pain and physical function in participants with moderate-to-severe osteoarthritis (OA) of the hip or knee." (PMID 35351194, 2022). "Nerve growth factor (NGF) inhibitors may have benefits for chronic pain, and the U. S. Food and Drug Administration has recently accepted regulatory submission of tanezumab (an anti-NGF agent) for osteoarthritis." (PMID 33981217, 2021).
osteoarthritis (continued). "However, the clinical development of tanezumab has been terminated due to the risk of induction of rapidly progressive osteoarthritis (RPOA), and no other NGF antibodies have been examined for their ability to treat diabetic neuralgia in either animal models or clinical trials." (PMID 35417079, 2022). "In clinical trials involving anti-nerve growth factor (NGF) treatments, these types of rapidly progressive osteoarthritis are generally observed (though not always) in joints with pre-existing osteoarthritis." (PMID 38646213, 2024). "Nerve growth factor (NGF) monoclonal antibodies inhibit chronic pain, yet failed to gain approval due to worsened joint damage in osteoarthritis patients." (PMID 39589827, 2024). "When an anti-NGF antibody was injected intra-thecally (IT) in C57Bl/6 mice at 13 weeks after PMM surgery, there was no improvement in pain reduction from chronic osteoarthritis." (PMID 36292950, 2022). "Bedinvetmab (Librela®), a fully canine anti-nerve growth factor monoclonal antibody, was compared to the non-steroidal anti-inflammatory drug (NSAID) meloxicam in dogs for the management of osteoarthritis-related pain in a randomised, open-label, multicentre, parallel-group study." (PMID 40196808, 2025). "The mechanism responsible for osteoarthritis in patients treated with NGF mAbs is not understood, and whether NRP1 differentially regulates the pronociceptive and protective actions of NGF in joints is unknown." (PMID 39589827, 2024). "No rapid progression of osteoarthritis (RPOA) was observed even at high doses, which was the most prominent concern when the US Food and Drug Administration shelved the development plan of similar anti-NGF drugs." (PMID 36578547, 2022). "Anti-NGF medicines have not yet received approval from the US Food and Drug Administration (FDA), although the FDA recently accepted regulatory submission for tanezumab, an anti-NGF medicine, to treat patients with osteoarthritis." (PMID 33480861, 2021).
diabetes (104 papers, 2003 to 2025). "Mechanistically, in a preclinical study, diabetes-induced oxidative stress, particularly through peroxynitrite formation, disrupts the proteolytic conversion of proNGF to NGF, causing an accumulation of proNGF and a concomitant reduction of mature NGF." (PMID 41471293, 2025). "Taurine found in the retina fights oxidative stress, especially in diabetes, and helps restore deficient levels of nerve growth factor, required for maintaining retinal health." (PMID 29258224, 2017). "Earlier work showed that diabetes-induced breakdown of the blood retina barrier was associated with increases in proNGF and decreases in NGF." (PMID 26807305, 2015). "In experimental STZ-diabetes rat model, decreases in NGF were associated with early retinal neurodegeneration." (PMID 25853140, 2015). "The imbalance in proNGF/NGF during diabetes was associated with alteration and expression of TrkA and p75NTR receptors." (PMID 26807305, 2015). "Impaired balance of proNGF and NGF was induced by peroxynitrite in Diabetes, which then causes neurovascular injury." (PMID 24040063, 2013). "These diabetes-induced NGF modifications are associated with the activation of JNK and p38, with the repression of the transcription factor Nf-κB and with the upregulation of the ion channel TRPV1." (PMID 23710226, 2013). "There is a deficiency of NGF in diabetes, and reduced levels or activity of NGF plays a significant role in the pathogenesis of diabetic neuropathy." (PMID 22927874, 2012). "In STZ-diabetic rats, oral cinnamon lowered hyperglycaemia and body weight while raising NGF and TrkA in both islets and exocrine pancreas, implying NGF-linked cytoprotection that may limit diabetes-related complications." (PMID 41471293, 2025). "Thus, it can be concluded that NGF is essential in controlling insulin discharge and blood sugar metabolism, and it is involved in the risk of developing diabetes complications." (PMID 37189822, 2023). "Synthesis of NGF is reduced in diabetes because of insulin deficiency and Schwann cell damage, whereas a decrease in NGF can result in axoplasmic transport and negative effects on NGF receptor expression, which affects the regulation of related gene expression and ultimately neurotrophy." (PMID 31131042, 2019). "Finally, a decrease in serum NGF level has been associated with peripheral neuropathy in animal models and humans with diabetes." (PMID 19534767, 2009). "The exact mechanism of sensitization of TRPV1 is not clear, but could be due to over compensation by other tropic factors, such as NGF in response to insulin deficiency or elevated PKC activity in diabetes." (PMID 15857517, 2005). "However, islet transplantation can restore the decreased NGF level caused by diabetes." (PMID 37189822, 2023). "NGF is a target-derived protein that regulates the phenotype and sensibility of nociceptor fibers, and its deficiency may lead to the development of clinical diabetes small fibers neuropathy." (PMID 36359415, 2022). "Additionally, reduced hyperalgesia after electroacupuncture was associated with lower upregulation of NGF in a diabetes model and decreased NMDA receptor phosphorylation as well as lower density of the NMDA subunit (NR2B) in a model of irritable bowel syndrome." (PMID 31354400, 2019). "These convergent findings establish NGF as a mechanistic keystone in diabetes-related tissue damage and also as a viable target for intervention, as well as a candidate biomarker for early detection of tissue distress and for monitoring therapeutic responses." (PMID 41471293, 2025). "Across experimental diabetes, NGF levels are context-dependent and these differences matter because they align with the time point, tissue compartment, animal strain/model, and concomitant interventions assessed." (PMID 41471293, 2025). "In diabetes, the equilibrium between mature NGF and proNGF is frequently disrupted, with a relative predominance of proNGF." (PMID 41471293, 2025).
diabetes (continued). "To verify the expression levels of NGF and Sirt1 in the pancreatic islets, we analysed pancreatic tissues from clinically diagnosed patients with diabetes via immunohistochemical and immunofluorescence staining." (PMID 41181709, 2025). "In diabetes, a disrupted balance between mature NGF and its precursor proNGF, favors the detrimental p75NTR pathway, leading to increased cellular stress, inflammation and apoptosis." (PMID 41471293, 2025). "A small number of clinical trials have explored NGF-based interventions in patients with diabetes and its complications." (PMID 41471293, 2025). "This altered NGF/proNGF ratio favors p75NTR-mediated apoptotic pathways, thereby contributing to the pathophysiology of diabetes-related complications by exacerbating cellular stress, promoting apoptosis and impairing tissue repair mechanisms." (PMID 41471293, 2025). "Upstream regulator analysis highlighted altered neurotrophic signaling in diabetes, with enhanced NGF/TRKA and diminished BDNF/TRKB activity, potentially driven by target-derived cues." (PMID 40667173, 2025). "Together, these strategies will help ensure that promising mechanistic insights about NGF translate into tangible improvements in the prevention and treatment of diabetes complications." (PMID 41471293, 2025). "Taken together, pharmacological human studies of the NGF axis in diabetes remain heterogeneous and context dependent." (PMID 41471293, 2025). "We included both clinical and preclinical studies focusing on NGF/proNGF biology and interventions across major diabetes complications." (PMID 41471293, 2025). "In type 2 diabetes mellitus, NGF levels are also elevated, as shown by the notably higher urinary NGF levels in these cases." (PMID 37373824, 2023). "In animal studies, exogenous mouse NGF can affect the occurrence and development of mechanical hyperalgesia and can alleviate neuropathic pain in a model of diabetes." (PMID 37593350, 2023). "The diabetes + saline treatment group exhibited significantly lower levels of NGF in the sciatic nerve (44.5 ± 2.1 pg/mg) compared to the control group (75.9 ± 5.7 pg/mg) (p < 0.01)." (PMID 38055406, 2023). "There is evidence in the literature that NGF is also related to diabetes, a clinical condition that is also characterized by inflammatory processes playing an important role in glucose tolerance and insulin sensitivity dysregulation." (PMID 37373824, 2023). "Our findings suggest that NGF prevents diabetes-driven retinal neurodegeneration, even when administered after a significant RNFL/GCL thickness reduction." (PMID 37628852, 2023). "The aims of our study were to clarify the natural history of diabetes-driven retinal neurodegeneration and to verify the possibility to prevent DR using topical nerve growth factor (NGF)." (PMID 36172176, 2022). "In diabetics, there was an early length-dependent dysfunction of small-diameter sensory fibers, with depletion of skin NGF and the sensory neuropeptide substance P." (PMID 35874807, 2022). "In contrast, ocular administration of exogenous NGF reverses TrkA impairment and counteracts gliosis, pro-apoptotic proNGF increase, and consequent RGC loss, following optic nerve lesions, and diabetes." (PMID 36291113, 2022). "Since blood NGF levels can be raised in cardiovascular diseases, bladder cancer, and bladder nephrolithiasis, as well as some neurological diseases or diabetes, it appears that the most specific and sensitive method is assessment of urine NGF." (PMID 35207243, 2022). "A weak diffuse cytoplasmic NGF immunoreactivity was detected in the islets of Langerhans of diabetes group whereas a moderate diffuse cytoplasmic NGF immunoreactivity was detected in the diabetes+cinnamon group in the female and male rats." (PMID 34174790, 2021). "In our research, we detected that the NGF immunoreactivity decreased in the islets of Langerhans of rats in the diabetes groups and increased in diabetes+cinnamon groups." (PMID 34174790, 2021).
diabetes (continued). "On the evaluation of histologic investigation of the pancreatic tissue, after the diabetes was formed, the research suggested that the decrease of cell number in the islets of Langerhans, NGF and Trk-A protein levels was as it was in the western blot analysis." (PMID 34174790, 2021). "Nerve growth factor (NGF) administration was also shown to reduce RGC apoptosis in the STZ-treated rat as assessed 15 weeks after diabetes onset." (PMID 34902066, 2021). "In many articles, NGF expression was shown to be increased in diabetes mellitus and it has been proven to be an important protective factor in diabetic neuropathy and vasculopathy." (PMID 33292292, 2020). "TRPV1 and substance P are known to be regulated by NGF and have been related to diabetes-induced neuropathy Mediators of inflammation, particularly the proinflammatory cytokines IL-1β and TNF-α play critical roles in various neuropathic pain conditions." (PMID 32104520, 2020). "In the present model of alloxan-induced diabetes, there was a downregulation of retinal NGF expression and a decline in the protein level." (PMID 31736682, 2019). "Pre-emptive gene therapy with NGF prevented bone marrow denervation, contrasting with the inhibitory effect of diabetes on the mobilisation of NK1R-expressing stem cells, and restored blood flow recovery from limb ischaemia." (PMID 31016359, 2019). "The cross-talk between NGF and insulin pathways downstream the insulin receptor suggests novel potential therapeutic targets to slow cognitive decline in AD and diabetes-related brain insulin resistance." (PMID 29736736, 2019). "In summary, the activation of NGF/TrkA signaling pathway improves the erectile function of rats with diabetes mellitus, which suggests a promising perspective in the future clinical practice." (PMID 29285284, 2017). "Endogenous levels of NGF have been shown to be altered in human and experimental diabetes, while p75NTR was shown to regulate glucose homeostasis and insulin sensitivity in diabetes." (PMID 28861085, 2017). "Administration of STZ reproduces not onlythe reduced NGF level typical of diabetes, but also the increased proNGF level." (PMID 28740732, 2017). "The history of NGF in clinical trials of Diabetes is exemplary with respect to the potentiality of NGF in the care of peripheral neuropathies." (PMID 27439311, 2016). "Diabetes is a metabolism disorder characterized by degeneration of peripheral neuron/fibers and altered local levels of NGF/NGF receptors and deregulation of NGF signal pathway." (PMID 27439311, 2016). "In parallel, our recent study showed that diabetes-induced imbalance of proNGF/NGF observed in aqueous humor fluid was mirrored in the serum of the same PDR patients (Table-1)." (PMID 26807305, 2015). "In our previous study of DA9801, a mixture of Dioscorea japonica and Dioscorea nipponica extracts showed a peripheral nerve protection effect in rats with STZ-induced diabetes through induction of endogenous NGF." (PMID 25878713, 2015). "Restoring NGF/proNGF balance using these treatments prevented diabetes-induced retinal neurodegeneration and vascular permeability." (PMID 26807305, 2015). "We and others have demonstrated protective effects of restoring NGF in experimental models of diabetes." (PMID 25853140, 2015). "Treatments that enhanced the levels of NGF either endogenously or by exogenous supplement of recombinant NGF protein prevented retinal neurodegeneration in models of diabetes." (PMID 25853140, 2015). "Further characterization of diabetes-induced imbalance in the proNGF to NGF ratio will facilitate its utility as an early biomarker for diabetic complications." (PMID 25853140, 2015). "This commentary aims to highlight the impact of diabetes-impaired balance of neurotrophins and in particular, the NGF and its receptors; TrkA and p75NTR in the pathology of DR." (PMID 26807305, 2015).